TIGIT (T cell immunoreceptor with Ig and ITIM domains)
Diseases named in the same sentence as TIGIT in open-access papers (continued):
Sharing a sentence is not in itself a finding about the gene and the disease.
breast carcinoma (73 papers, 2017 to 2025). "For example, Fusobacterium nucleatum, which has been linked to colorectal and breast cancer, interacts with TIGIT and CEACAM1 on the surface of CD4+ T cells, inhibiting their cytotoxic potential." (PMID 40943371, 2025). "Other studies reported that TIGIT gene upregulation is associated with improved clinical outcome in a series of breast cancer (all types), and in the basal subtype." (PMID 36544779, 2022). "The elevated average expression of TIGIT was significantly associated with better OS (HR: 0.35 (0.17–0.74); P=0.0037) in luminal B breast cancer." (PMID 32602545, 2020). "Despite multiple lines of evidence support that TIGIT plays a pivotal role in limiting adaptive and innate immunity against tumors, the role of TIGIT and its association with tumor immune microenvironment in breast cancer remains largely unknown." (PMID 33721026, 2021). "In breast cancer cohorts, LAG-3 expression is associated with markers of T-cell exhaustion and co-inhibitory molecules such as TIGIT and PD-L1, indicating its potential role in regulating T-cell dysfunction and impairing anti-tumor immune responses." (PMID 41550427, 2025). "In early-stage breast cancer, high co-expression of TIGIT and other immune checkpoint receptors—including PD-1, CTLA-4, LAG-3, and TIM-3—on tumor-infiltrating lymphocytes correlates with increased disease aggressiveness." (PMID 39717767, 2024). "TIGIT is upregulated by T cells in a wide range of human solid tumors, such as lung cancer, urologic cancer, and breast cancer compared with normal tissue." (PMID 37291608, 2023). "We recently reported that the new generation ICRs TIM-3, LAG-3, and TIGIT are highly expressed in locally advanced breast cancer with poor prognostic factors following neoadjuvant chemotherapy." (PMID 36271406, 2022). "For example, the blockade of TIGIT was found to positively regulate the response of NK cells against breast cancer cell lines." (PMID 35465350, 2022). "Extensive analysis of gene databases also revealed a beneficial role of TIGIT in head and neck or breast cancer, while in renal clear cell carcinoma, tumors expressing TIGIT demonstrated poorer patient outcomes." (PMID 36551992, 2022). "In another study, using large-scale transcriptome data analysis of aggressive breast cancers, TIGIT was found to be highly and specifically expressed in aggressive breast cancer, and its pro-tumor activities were linked to immune-related genes." (PMID 35656508, 2022). "Tegaserod maleate inhibits the progression of breast cancer, and its combination with anti-TIGIT can effectively inhibit tumor growth and improve the sensitivity of immunotherapy in breast cancer." (PMID 35154317, 2022). "In mice injected with EMT6 breast cancer cells, it has been observed that the simultaneous blockade of TIGIT and PD-1 induces stronger anti-tumor immune effects and achieves a complete response (CR)." (PMID 36612100, 2022). "Our study indicates that TIGIT and PD‐1 are relevant targets for checkpoint inhibition in breast cancer that warrants testing also in the non‐metastatic setting to prevent metastasis." (PMID 34165864, 2022). "Preclinical in vivo studies using colon and breast cancer models demonstrated strong synergistic anti‐tumor effects when anti‐TIGIT blockade was combined with targeting of PD‐1." (PMID 34165864, 2022). "High levels of TIGIT and its ligand PVR (poliovirus receptor, CD155) are significantly associated with low overall survival and recurrence-free survival of patients with breast cancers." (PMID 36612100, 2022). "For instance, TIGIT in colorectal cancer and TIGIT plus PD-L1 in colorectal cancer and breast cancer were found hypomethylated at the gene promoter level." (PMID 35656508, 2022). "The number of human NK cells expressing the PVR receptor CD112R or TIGIT (CD56+) decreases with decreased IFN-γ production in CD112-positive breast cancer, indicating that CD112R engagement with the ligand CD112 suppresses NK cell cytotoxicity." (PMID 34433460, 2021).
breast carcinoma (continued). "We uncovered the relationship between TIGIT and major molecular and clinical characteristics in breast cancer." (PMID 33721026, 2021). "As expected, TIGIT expression was significantly up-regulated in higher malignant pathological type breast cancer." (PMID 33721026, 2021). "The ligand of TIGIT, poliovirus receptor (PVR) was reported to be associated with more aggressive breast cancer subtypes such as HER2 positive and TNBC, which is consistent with our results." (PMID 33721026, 2021). "In vitro evidence support that blocking TIGIT or PVR resulted in enhanced immune cell-mediated lysis of breast cancer cell lines." (PMID 33721026, 2021). "A recent study by Stammet al. showed that the use of an anti-PVR or anti-TIGIT monoclonal antibody (mAb) resulted in increased lysis of breast cancer cell lines by cytokine-induced killer cells." (PMID 32489646, 2020). "In preclinical models of colorectal and breast carcinoma, TIGIT blockade was shown to reverse the exhaustion phenotype of cytotoxic T cells and to inhibit tumor growth." (PMID 32188505, 2020). "TIGIT is preferentially expressed on CD16+NK cells, and blockade of TIGIT significantly augmented trastuzumab-triggered NK cell-mediated anti-tumor immune responses against breast cancer." (PMID 32714324, 2020). "We also analyzed the expression characters of other immune checkpoints such as PD-1, PD-L1, TIM3, LAG3, and TIGIT in breast cancer tissue." (PMID 33250890, 2020). "High expression levels of CTLA-4 and TIGIT were correlated with favorable prognosis in breast cancer." (PMID 32602545, 2020). "Recent studies demonstrated that blockade of TIGIT significantly enhances anti-tumor NK cell activity against breast cancer and endometrial cancer, and can bypass MDSC-mediated supression." (PMID 32153582, 2020). "In humans, blockade of PVRIG and TIGIT has been shown to enhance trastuzumab-mediated NK cell response against breast cancer." (PMID 31234588, 2019). "In this study, we developed a CD155-based CAR comprising the extracellular domain of the human TIGIT, 4-1BB, and CD3z signaling domains and utilized a murine model of cervical and breast cancer to comprehensively evaluate the antitumor responses elicited by the CD155-based CAR T cells." (PMID 41394877, 2025). "However, multiple research groups have discovered the overexpression of TIGIT in natural killer (NK) cells and T cells within peripheral blood mononuclear cells (PBMCs) that exhibit an exhausted phenotype in cervical and breast cancer." (PMID 41394877, 2025). "TIGIT plays a role in immune and inflammatory responses similar to PD-1 in breast cancer, suggesting that TIGIT and PD-1 may synergistically promote the development of severely dysfunctional T cells, as reported in other cancers." (PMID 39717767, 2024). "Our data indicate that TIGIT expression is closely related to breast cancer invasiveness." (PMID 35770416, 2023). "TIGIT blockade using a monoclonal antibody resulted in delayed tumor growth, reduced metastasis, improved survival, and the reversed exhaustion of tumor-infiltrating NK cells in preclinical models of colon cancer, breast cancer, and fibrosarcoma." (PMID 35327475, 2022). "Accordingly, TIGIT expression seems closely related to higher malignant pathological types of breast cancer and might be a potential biomarker of breast cancer progression." (PMID 35656508, 2022). "Dual blocking of TIGIT and PD-1 inhibits tumor growth in a mouse model of breast cancer." (PMID 36612100, 2022). "Counter-intuitively, TIGIT gene expression was associated with improved recurrence-free survival (RFS) and OS in basal-like breast cancers, a subpopulation that predominantly includes TNBC, and also in a cohort of patients with all breast cancer types." (PMID 36544779, 2022). "TM inhibited the progression of breast cancer, and its combination with anti-TIGIT could effectively inhibit tumor growth and improve the sensitivity of immunotherapy in breast cancer." (PMID 35154317, 2022).
breast carcinoma (continued). "Interestingly, high expression levels of CTLA-4 and TIGIT were correlated with favorable prognosis in breast cancer." (PMID 35646057, 2022). "Moreover, we also found that high expression of TIGIT was highly enriched in more aggressive breast cancer subtypes, including higher tumor grade, TNBC subtype, basal-like subtype and HER2-enriched subtype." (PMID 33721026, 2021). "It is most likely that these malignant biologic behaviors have contributed to tumor recurrence and therapy resistance, which implicates that mechanism of TIGIT in breast cancer might be the key to triumphing over this deadly disease." (PMID 33721026, 2021). "Interestingly, we found that TIGIT played almost exactly the same role in immune and inflammatory response as PD-1 in breast cancer." (PMID 33721026, 2021). "In summary, TIGIT expression is closely related to the aggressiveness of breast cancer and might be a potential biomarker." (PMID 33721026, 2021). "Multiple lines of evidence support that TIGIT might be an intriguing candidate for immunotherapy of breast cancer in the future." (PMID 33721026, 2021). "In summary, TIGIT expression was tightly related to the aggressiveness of breast cancer; TIGIT might manipulate anti-tumor immune responses by impacting not only T cells but also other immune cells." (PMID 33721026, 2021). "Herein, we analyzed the TIGIT expression in the RNA-seq data of 2994 breast cancer patients." (PMID 33721026, 2021). "CTLA-4 and TIGIT were correlated with better prognosis in breast cancer." (PMID 32602545, 2020). "To determine whether these combined predictors of cancer prognosis were applicable in breast cancer, we additionally examined the expression of PD-1, PD-L1, TIGIT, TIM3, and LAG3 in breast cancer tissue microarrays." (PMID 33250890, 2020). "Recently, it has been described the expression of TIGIT in different murine tumor cell lines (colon cancer, breast cancer, melanoma and lung carcinoma) and human colorectal cancer that delivers inhibitory signals to CD8+ T cells and NK cells by engaging with CD155 expressed on these immune cells." (PMID 31234588, 2019). "However, TIM-3 and TIGIT targeting are still early in clinical research, and few reports of the therapeutic efficacy of anti-TIGIT or anti-TIM-3 including combinatorial therapies (TIGIT ICI or TIM-3 ICI plus PD-1(L1) ICI) are available in breast cancer to date." (PMID 33717059, 2021). "Furthermore, TIGIT might synergize with other immune checkpoint molecules to regulate the immune microenvironment in breast cancer, which shed novel sights for developing new targeted drugs for immunotherapy." (PMID 33721026, 2021). "Our work further supports that TIGIT might be a promising target for breast cancer immunotherapy, future work focused on elaborating the potential synergistic role between TIGIT and other immune check point molecules will provide novel sights for combination immunotherapy." (PMID 33721026, 2021). "Together, these data indicated that TIGIT and PD-1 might play a synergistic role in tumor immune and inflammatory response to promote the development of a severe dysfunctional phenotype in T cells in breast cancer as reported in other cancers." (PMID 33721026, 2021). "In line with our data positive (co-) expression of TIGIT and PVRIG or CD39 was recently detected on CD8+ T cells derived from the primary site of several tumor types including lung, breast cancers and acute leukemia." (PMID 40274631, 2025). "The interaction between TIGIT and NECTIN2 has been demonstrated to play a critical immune checkpoint regulatory role within the tumor immune microenvironment of breast carcinoma and neuroblastoma." (PMID 40855305, 2025). "Elevated levels of TIGIT, TIM-3, and LAG-3 are found in locally advanced breast cancer patients with poor prognostic factors following neoadjuvant chemotherapy." (PMID 39717767, 2024).
breast carcinoma (continued). "Recent research has illustrated that the TIGIT-NECTIN2 pathway drives immune cells toward an immunosuppressive and exhausted state in hepatocellular carcinoma and breast cancer." (PMID 39334513, 2024). "An anti-TIGIT mouse mAb, called 13G6, was produced and used to block TIGIT activity in a CT26 colon cancer, 4T1 mammary cancer, or methylocholanthrene (MCA)-induced fibrocarcinoma mouse model." (PMID 39339180, 2024). "The combination of TIGIT and CD112R inhibition by Xu and colleagues led to enhanced NK-cell-mediated ADCC against breast cancer cells coated with trastuzumab in vitro." (PMID 39339180, 2024). "Hypomethylated promoters with the upregulated gene expressions of PD-1, CTLA4, and TIM3 are reported in primary breast cancer tissues, and CTLA4 and TIGIT promoters in colorectal cancer tissues." (PMID 37460953, 2023). "Relative to luminal A and B, TIGIT was significantly upregulated in HER2 overexpressing and basal type breast cancer (p=<0.01)." (PMID 35770416, 2023). "Transcriptomic analyses showed that both TIGIT and PVR are overexpressed in TNBC compared with other breast cancer types." (PMID 36544779, 2022). "It has also been examined the levels and prognostic values of 50 ICR genes in molecular subgroups of breast cancer, including PD-1, CTLA-4, TIGIT, LAG-3, and TIM-3." (PMID 36271406, 2022). "Our research shows, for the first time, that the TIGIT blockade can reverse defective NK cell function in patients with MDS, consistent with previous reports in colon and breast cancers." (PMID 36303184, 2022). "On immune checkpoint genes in breast cancers, POGLUT2 was positively correlated with CTLA4, CD274, TIGIT, LAG3, and PDCD1." (PMID 36158688, 2022). "Furthermore, we further analysis the correlation of risk score and immune checkpoint in breast cancer and demonstrated that most of key checkpoint were significantly differentially expressed between the two groups in breast cancer patients, including CD44, TIGIT, CTLA4, CD274, CD86 and CD80." (PMID 35052427, 2021). "Xu and coworkers showed that blockade of TIGIT and CD112R separately or together improves the effect of trastuzumab on breast cancer by enhancing NK cell activity." (PMID 34433460, 2021). "The expression of Treg-related genes involving Treg-suppressive function was largely unchanged between CD177+ and CD177− TI Treg cells in human breast cancer or ccRCC, with slight elevation of ICOS, TIGIT, and CTLA4." (PMID 34599187, 2021). "High mRNA expression of TIGIT was significantly connected to favorable OS (HR: 0.67 (0.49–0.92); P=0.012) and RFS (HR: 0.77 (0.66–0.9); P=0.0011) in breast cancer patients." (PMID 32602545, 2020). "Then, we validated the protein expression of immune checkpoint molecules (VISTA, PD-1, PD-L1, TIGIT, TIM3, and LAG3) in 324 human breast cancer samples by immunohistochemistry and quantitative immunofluorescence (QIF) approaches." (PMID 33250890, 2020). "In this study, the expression patterns of immune checkpoints, such as PD-1, CTLA-4, TIGIT, and LAG3, are quite different from that of VISTA in breast cancer microenvironment." (PMID 33250890, 2020). "For the anti-TIGIT antibody (A15153G), we were able to show in previous studies that its use leads to increased T-cell and NK cell-mediated lysis of acute myeloid leukemia (AML) cells or breast cancer cells." (PMID 40274631, 2025). "However, single-cell transcriptomic sequencing of breast cancer cells that metastasized to the liver and brain showed that the expression of the immunoreceptor inhibitory checkpoint genes, LAG3 and TIGIT, in T cells was higher than that of PDCD1 (PD-1)." (PMID 38462658, 2024). "In vitro analysis showed that blockade of PVRIG or TIGIT increased the number of IFN-γ-producing NK cells under co-culture of breast cancer cells, and the combination of anti-PVRIG and anti-TIGIT antibodies induced a further increase in IFN-γ-producing NK cells and improved cytotoxicity of NK cells." (PMID 39156900, 2024).
breast carcinoma (continued). "Moreover, the expression of LAG3, CTLA-4, PD-L1, CD274, TIGIT, HAVCR2 and PDCD1LG2 was upregulated in the TFRC high-expression group compared with the TFRC low-expression group in breast cancer." (PMID 35847985, 2022). "Multiple IRs expression, such as PD-1, PD-L1, TIGIT, and CTLA4, was reported in detail in TILs and circulating T cells in primary breast cancer and colorectal cancer in which immune checkpoint expression was correlated with promoter demethylation and post-translational histone modifications." (PMID 35656508, 2022). "TIGIT and HIF-1α activity suppression experiments, using a siRNA carrier system, have revealed a critical role of these molecules in tumor growth, apoptosis, and metastasis in colorectal and breast cancer." (PMID 35656508, 2022). "CTLA-4 and TIGIT were related to longer OS and RFS in breast cancer patients." (PMID 32602545, 2020). "A study on breast cancer patients with liver or brain metastases who responded poorly to anti-PD-1 therapy found that targeting LAG3 in combination with other co-inhibitory receptors, such as TIGIT, represents a potential therapeutic strategy for tumors with low PD-1 expression." (PMID 40411616, 2025). "In particular, high-frequency PD-1−TIGIT + CD8+ tumor-infiltrating lymphocytes (TILs) were observed in TNBC cells, making the strategy of dual PD-1/TIGIT blockade a promising therapeutic approach via increasing CD8+ TIL function in TNBC, which may further improve the immunotherapy for breast cancer." (PMID 36765782, 2023). "Therefore, targeting the LAG3‐LGALS3 and TIGIT‐NECTIN2 pairs may be an effective strategy for treating liver and brain metastases of breast cancer." (PMID 36529697, 2023). "Investigation of Treg subsets in blood and primary tumor biopsies from breast cancer patients demonstrated phenotypic similarity between Treg fraction II in blood, corresponding to activated Tregs, and intratumoral Tregs with high expression of CTLA‐4, TIGIT, and ICOS." (PMID 34165864, 2022). "In this study, TIGIT involvement in anti-tumor CD8+ responses was investigated, and TIGIT was shown to be highly expressed on TILs in human lung squamous cell carcinoma, colon adenocarcinoma, uterine corpus endometroid carcinoma, breast cancer, and renal clear cell carcinoma." (PMID 35327475, 2022). "It is possible that targeting alternative checkpoints such as TIGIT and Tim-3, largely expressed on T cells, as well as therapies against NK cell checkpoints, such as killer cell immunoglobulin-like receptors (KIR; also known as CD158) and NKG2A, will be effective in HR+ breast cancer." (PMID 34135901, 2021). "Moreover, the finding that their expression levels were associated with PD-1+ and PD-L1+ cells supports the development of combination strategies to concomitantly target the PD1-PD-L1 and TIGIT-PVR axes in this highly aggressive breast cancer subtype, particularly in non-molecular apocrine TNBC." (PMID 36544779, 2022).